NPM1 (nucleophosmin 1)
Diseases named in the same sentence as NPM1 in open-access papers (continued):
Sharing a sentence is not in itself a finding about the gene and the disease.
colorectal cancer (21 papers, 2011 to 2026). A primary or metastatic malignant neoplasm that affects the colon or rectum. "Using Npm1-haploinsufficient (Npm1+/−) mice, we observed increased susceptibility to colitis and colitis-associated colorectal cancer." (PMID 39103576, 2024). "Similarly, elevated NPM1 levels are linked to lymph node metastasis and reduced survival rates in patients with colorectal cancer." (PMID 40705480, 2025). "In this study, we proved that PD-L1 transcription was activated by NPM1 in melanoma and colorectal cancer cells as well." (PMID 38243170, 2024). "For example, DDX27 was reported to enhance NF-κB signaling by increasing nucleophosmin-1 (NPM1) and NF-κB-p65 interaction in colorectal cancer." (PMID 35370459, 2022). "NSC348884 was initially shown to promote monomerization of NPM1 in LNCaP (androgen-sensitive prostate adenocarcinoma) and HCT116 (colorectal carcinoma) cell lines, in which NPM1 is wild-type and highly expressed." (PMID 27058426, 2016). "Here we examined the function of NPM1 in IBD and colitis-associated colorectal cancer (CAC)." (PMID 39103576, 2024). "Notably, NPM1 facilitated the activation of AKT signaling in colorectal cancer, while IQGAP2 could also influence the activation of the AKT pathway." (PMID 39039052, 2024). "Moreover, PVT1 expression was up-regulated in colorectal cancer tissues, which correlated with the expression of MYC and many MYC regulating genes FUBP1, EZH2, and NPM1." (PMID 29108264, 2017). "Moreover, NPM1 contributed to cell proliferation through phosphatase and tensin homologue deleted on chromosome ten (PTEN) inactivation, while NCOA5 promoted proliferation, migration and invasion of colorectal cancer cells via activation of PI3K/Akt pathway." (PMID 34922560, 2021).
myeloproliferative neoplasm (20 papers, 2012 to 2025). A clonal hematopoietic stem cell disorder, characterized by proliferation in the bone marrow of one or more of the myeloid (i.e., granulocytic, erythroid, megakaryocytic, and mast cell) lineages. "Mutation in both Dnmt3α and Npm1 (nucleophosmin 1) causes clonal haematopoiesis followed by myeloproliferative disorder and successively acute myeloid leukaemia (AML)." (PMID 36982935, 2023). "While human NPM1 mutations are most often observed in de novo AML, several studies have shown that NPM1 mutations can be present in MDS or MDS/myeloproliferative neoplasm (MPN) prior to blast counts reaching the threshold for AML diagnosis." (PMID 30692594, 2019). "Induction of mutant Npm1 after development of Dnmt3a-mutant CH causes progression to myeloproliferative disorder (MPD), and more aggressive MPD is observed with longer latency between mutations." (PMID 30692594, 2019). "One “conventional” knock-in model of NPM1 mutation demonstrated that NPM1 mutation can result in myeloproliferative disease but is insufficient for leukemogenesis." (PMID 24895580, 2014). "The NPM1 mutation induces a myeloproliferative disorder, but evidence indicates that other insults are necessary for the development of AML." (PMID 22348345, 2012). "Different models of NPM1 mutations show that it induces myeloproliferative disorders." (PMID 34944812, 2021). "For example, expression of the cytoplasmic NPM1 mutant (NPMc+) under the human myeloid-specific MRP8 promotor or in a conventional knockin mouse model induced myeloproliferative disease." (PMID 34944812, 2021). "The Msi2 reporter also marked LSCs in chronic myeloid leukemia and in an NPM1-driven model of myeloproliferative disease." (PMID 33243988, 2020). "By itself NPM1 expressed in haemopoietic stem cells produces a myeloproliferative disorder and a low penetrance of late occurring AML." (PMID 30568172, 2019). "Mice with a targeted Flt3ITD mutation develop myeloproliferative neoplasms (MPN), and several other mutations (e.g. Npm1, Tet2 and Runx1 mutations) cooperate with Flt3ITD to drive AML in mice much as in humans." (PMID 27879203, 2016). "FLT3-ITD, NPM1, and DNMT3A mutations frequently occurred in AML patients and have been found conferred with myeloproliferative neoplasms in mouse model." (PMID 24895580, 2014). "UPN09 was diagnosed with secondary AML (prior diagnosis of myeloproliferative neoplasm (MPN); AML not otherwise specified (NOS), AML without maturation, normal male karyotype, no BCR–ABL1 fusion, no CEBPA, FLT3, or NPM1 mutation) in 2008." (PMID 34950586, 2021). "However, it should be noted that, though less frequently compared to de novo AML, NPM1 mutations have also been observed in sAML, progressing from either MDS or myelodysplastic/myeloproliferative neoplasms (MDS/MPN), with a variable incidence around 10–15% and ranging from 4.5% to 27% of the cases." (PMID 33255988, 2020). "Conventional transgenes in which expression of mutated NPM1 was regulated by the human MRP8 promoter and a knock-in model mimicking the human mutation in the mouse Npm1 developed myeloproliferative disease only but no AML." (PMID 30669675, 2019).
hepatocellular carcinoma (19 papers, 2007 to 2024). A malignant tumor that arises from hepatocytes. "Multifactorial Cox regression of 11 prognostic genes resulted in seven independent risk genes affecting the prognosis of patients with hepatocellular carcinoma, namely ENO1, NDRG1, NPM1, H2AX, IL33, MT3 and TXNRD1." (PMID 38097352, 2023). "NPM1 protein expression is upregulated in colorectal and hepatocellular carcinoma, promoting tumor migration and invasion." (PMID 37254219, 2023). "Another study also showed that increased NPM1 expression correlated with tumor progression in hepatocellular carcinoma, which was consistent with the current result." (PMID 22631075, 2012). "Moreover, to further explore the association between NPM1 expression and HCC patients’ clinical outcome, the TCGA hepatocellular carcinoma cohort was analyzed." (PMID 28874807, 2017). "A truncated form of NPM1 found in some hepatocellular carcinoma tissue formed an unusually stable oligomer and showed increased susceptibility to cleavage by granzyme B. Initiation of translation at the seventh methionine generated a protein (M7-NPM) that shared all these properties." (PMID 25490769, 2014). "NPM1 is a 37 kDa phosphoprotein with nucleo-cytoplasmic shuttling properties that is present at higher levels in proliferating cancer cells than in quiescent cells, and its increased expression in hepatocellular carcinoma correlates with clinicopathologic parameters." (PMID 18328103, 2008). "We also found that the expression of NDRG1, NPM1, TXNRD1 in the hepatocellular carcinoma samples from patients with poor prognosis were higher than the samples from patients with better prognosis." (PMID 38097352, 2023). "Compared with the paracellular tissues, the expression of NDRG1, NPM1, TXNRD1 were both increased in the hepatocellular carcinoma samples." (PMID 38097352, 2023). "PRKDC, PARP1, NPM1 and XRCC6 are hepatocellular carcinoma over-expression genes which modulate cell cycle regulation network through the modulation of UBC." (PMID 24564241, 2013). "Overall, NPM1 overexpression is linked to high grade tumors and poor prognosis, as observed in brain glioblastoma, oral squamous cell carcinoma, non-small cells lung cancer (NSCLC), hepatocellular carcinomas (HCC), colon cancer, ovarian cancer, and endometrial carcinoma." (PMID 27553022, 2016). "NPM1 has been defined as an autoantigen in systemic lupus erythematosus (SLE), scleroderma, and hepatocellular carcinoma (HCC)." (PMID 25490769, 2014).
endometrial cancer (15 papers, 2014 to 2024). Primary or metastatic malignant neoplasm involving the endometrium (mucous membrane that lines the endometrial cavity). "It has been reported that miR‐646 binds to the mRNA encoding nucleophosmin 1 (NPM1) in endometrial cancer and exerts a tumour suppressor effect." (PMID 32378344, 2020). "The present study was aimed to elucidate the role of NPM1 in different clinical stages of human endometrial carcinoma and the underlying mechanism of NPM1 action." (PMID 25663821, 2014). "And furthermore the level of NPM1 is strongly linked to the initiation and progression of endometrial carcinoma." (PMID 25663821, 2014). "In endometrial cancer, circRNA WHSC1 is upregulated, and overexpression of circRNA WHSC1 promotes the proliferation, migration and invasion and decreased apoptosis of endometrial cancer cells by targeting the miR‐646/nucleophosmin 1(NPM1) pathway." (PMID 36890830, 2023). "Circ_WHSC1 promotes proliferation, migration, and invasion and inhibits apoptosis in endometrial cancer by sponging miR-646 and targeting nucleophosmin 1 (NPM1)." (PMID 34829818, 2021). "In endometrial cancer, miR‐646 inhibits cell proliferation, migration and invasion, and targets NPM1 mRNA to negatively regulate the progression of endometrial cancer." (PMID 32378344, 2020). "NPM1 is highly expressed in endometrial cancer and correlates positively with the clinical stage and histological grade of endometrial cancer." (PMID 32378344, 2020). "Here, we demonstrate for the first time that nucleophosmin (NPM1/B23) suppression can restore the expression of estrogen receptor α (ESR1/ERα) in endometrial cancer cells." (PMID 27527851, 2016). "Recent research has found NPM1’s expression is associated with the presence of estrogen receptor-α (ERα) in Ishikawa and ARK1 endometrial cancer cells." (PMID 25663821, 2014). "A strong positive correlation between NPM1 level and the clinical stage and histological grade of endometrial carcinomas was observed." (PMID 25663821, 2014). "Expression of NPM1 was gradually increased with the increase of clinical stages of endometrial carcinomas." (PMID 25663821, 2014). "Our study using clinical samples showed that NPM1 is significantly more abundant in endometrial carcinoma tissues than in normal endometrial tissues." (PMID 25663821, 2014). "Recent studies on NPM1 and endometrial cancer have shown that the expression level of NPM1 has a positive regulatory effect on the proliferation, migration, and invasion of endometrial cancer cells 38, consistent with the results obtained in our in-vitro experiments." (PMID 38164189, 2024). "Therefore, we propose that circWHSC1 promotes the occurrence and development of endometrial cancer by the sponging miRNA‐646, thereby increasing the level of NPM1." (PMID 32378344, 2020). "CircWHSC1 promotes endometrial cancer development through sponging miR‐646 and targeting NPM1." (PMID 32378344, 2020). "With regards to prognostic issues, NPM1 has been associated with tumor grading in hepatocellular and endometrial carcinomas but not in oral squamous carcinoma." (PMID 26993766, 2016). "NPM1 was also required for the E2-induced proliferation of endometrial cancer cells." (PMID 25663821, 2014). "And NPM1 may be used as a new biomarker for judging the progression and prognosis of endometrial carcinoma." (PMID 25663821, 2014). "In the present study, we investigated NPM1 alteration in different clinical stages of endometrial carcinoma and analyzed the estrogen regulation of NPM1 expression in primary-cultured International Federation of Gynecology and Obstetrics (FIGO) stage I human endometrial adenocarcinoma cells." (PMID 25663821, 2014). "On the other hand, recent study confirmed the miR-646/NPM1 axis, an indicator for total active nucleoli, as critical for HOTAIR to control estrogen-induced viability, migration, and invasion of endometrial carcinoma cells." (PMID 33667269, 2021).
endometrial cancer (continued). "In endometrial carcinoma, lncRNA HOTAIR facilitated the expression of NPM1 by negatively regulating miR-646, and thereby promoting the proliferation, migration and invasion of EC cells." (PMID 32587476, 2020). "A previous study demonstrated that E2 increased NPM1 protein expression in an ERα-dependent manner in Ishikawa and ARK1 human endometrial cancer cell lines." (PMID 25663821, 2014). "The distribution and expression of NPM1 in normal endometrium, FIGO stages I to IV endometrial carcinoma tissues was analyzed using immunohistochemistry, RT-qPCR and Western blotting." (PMID 25663821, 2014). "However, the role of NPM1 in endometrial carcinomas is still not well-known." (PMID 25663821, 2014).
prostate carcinoma (15 papers, 2007 to 2025). A carcinoma that arises from epithelial cells of the prostate gland. "Nucleophosmin 1 (NPM1) is a multifunctional protein that promotes tumor progression in various cancers and is associated with a poor prognosis of prostate cancer (PCa)." (PMID 37875480, 2023). "NPM1 is also frequently overexpressed in solid tumors of different histological origin (such as gastric, colon, ovarian, and prostate carcinomas), however to date NPM1 mutations seem to be exclusively found in AML patients, although the relevance of splice variant expression remains undetermined." (PMID 29221119, 2017). "Previous studies have found that NPM1 expression had certain accuracy in predicting the prognosis of gastric cancer and prostate cancer." (PMID 34335635, 2021). "In this study, we report that the level of NPM1 in prostate cancer cells specifically regulates EGF expression and the MAPK (Mitogen Activated Protein Kinases) signalling pathway." (PMID 24796332, 2014). "We show that reducing NPM1 expression in LNCaP cells alters the clonogenic and proliferation capacities of these prostate cancer cells as well as their ability to migrate and to invade matrix-containing supports." (PMID 24796332, 2014). "In this regard, NPM1 was knocked-down in the LNCaP prostate cancer cell lines whose tumour characteristics such as migration, proliferation and invasion capacities are well established." (PMID 24796332, 2014). "NPM1 was described to potentiate the action of the androgen receptor (AR) in prostate cancer cells following a direct interaction with this transcription factor on chromatin." (PMID 24796332, 2014). "Overexpression of NPM1 has been reported in many types of major human solid tumors including colon, liver, stomach, ovary, bladder, breast and prostate carcinomas." (PMID 25663821, 2014). "Our previous findings showed that the molecular chaperone NPM1 is over-expressed in prostate carcinoma tissue, compared to control adjacent tissue where it stimulates the androgen-dependent transcription." (PMID 24796332, 2014). "To conclude, our data demonstrate that NPM1 is involved in the control of prostate cancer cell proliferation and invasion capacities both in vitro and in vivo." (PMID 24796332, 2014). "To further determine the role of NPM1 in prostate cancer, we analysed tumourigenesis of the shNPM1 LNCaP and shScr LNCaP prostate cancer cell lines in vivo following subcutaneous injection in the flank of male nude mice." (PMID 24796332, 2014). "To better understand NPM1 functions in prostate cancer cells, we sought to characterize its impact on prostate cancer cells behaviour and decipher the mechanisms by which it may act." (PMID 24796332, 2014). "Here we address the question whether NPM1 could potentiate proliferation, migration and invasion capacities of prostate cancer cells." (PMID 24796332, 2014). "Thereby, NPM1 is able to bind and to stabilize K-Ras in an active form, and may thus activate MAPK signalling as described in prostate cancer." (PMID 24796332, 2014). "We previously identified NPM1 (nucleophosmin 1) as one of the genes whose expression is significantly increased in prostate tumour cells when compared to non-tumour adjacent tissue, indicating that NPM1 could act as an enhancer of prostate cancer progression." (PMID 24796332, 2014). "Similarly NPM1 showed hints at elevated expression, but this was seen in only 5 out of a possible 18 samples compared to normal stroma, and is unlikely to be a uniformly altered protein in prostate cancer stroma." (PMID 26934553, 2016). "In order to better understand how NPM1 can promote prostate cancer cell behaviour, we performed a qPCR Array analysis (RT2 ProfilerTM array, PAHS-121A-2, Qiagen) and determined the nature of genes whose transcription levels are modulated by the knockdown of NPM1 (data not shown)." (PMID 24796332, 2014).